CX3CR1 (C-X3-C motif chemokine receptor 1)
Diseases named in the same sentence as CX3CR1 in open-access papers (continued):
Sharing a sentence is not in itself a finding about the gene and the disease.
preeclampsia (5 papers, 2009 to 2025). Preeclampsia is a hypertensive disorder of pregnancy that is characterized by new-onset hypertension with proteinuria presenting after 20 weeks of gestation, and depending on mild or severe forms may initially present with severe headache, visual disturbances, and hyperreflexia. "The significant underdevelopment of placental vascular network in preeclampsia is associated with the change in the CX3CL1/CX3CR1 system, especially in FGR complicated pregnancies." (PMID 33496844, 2021). "The aim of this study was to search for an association between V249I and T280M polymorphisms of CX3CR1, preeclampsia and endothelial dysfunction." (PMID 19587779, 2009). "Genotype, combined genotype and haplotype frequencies of the V249I and T280M polymorphisms of the CX3CR1 gene in the preeclampsia group, distributed according to severity and time of onset." (PMID 19587779, 2009). "This is the first study to characterize the CX3CR1 gene polymorphisms in patients with preeclampsia." (PMID 19587779, 2009). "While CX3CR1 is typically restricted to placental endothelial cells, preeclampsia is characterized by its aberrant expression on syncytiotrophoblasts alongside reduced endothelial CX3CR1, confirming dysfunctional angiogenesis as a central pathogenic mechanism." (PMID 41463301, 2025). "There was a moderate negative correlation between birth weight, V/EVTI and CX3CL1 serum level and CX3CR1 placental expression in the group of pregnancies complicated with preeclampsia." (PMID 33496844, 2021). "The appearance of CX3CR1 on syncytiotrophoblastic cells with concomitant low expression in endothelium in preeclamptic placentas seems to confirm the general pathogenesis of preeclampsia which can be described as a kind of a dysfunctional angiogenesis." (PMID 33496844, 2021). "For the correlations between CX3CR1 expression and birth weight, another model was selected, which showed the impact of preeclampsia at p = 0.001." (PMID 33496844, 2021). "For the correlation between CX3CR1 expression and vascularization index the multivariate regression model was created and showed significant weight of preeclampsia and FGR at p = 0.004." (PMID 33496844, 2021). "The fractalkine receptor CX3CR1, linked to increased angiogenesis in diabetic placentas and early-onset severe preeclampsia, was upregulated in our samples exposed to placental MVM and preeclampsia." (PMID 35471950, 2022). "Therefore, placental expression of CX3CL1/CX3CR1 in preeclampsia can be a part of a developed inflammatory reaction." (PMID 33496844, 2021). "Hence, reductions in mast cells and CX3CR1 expression might contribute to impaired villous vascular development in early-onset preeclampsia placentas." (PMID 34992598, 2021). "It seems that in the case of preeclampsia, we have a kind of insensitivity of placental vessels for the angiogenetic action of CX3CL1/CX3CR1, which is observed elsewhere." (PMID 33496844, 2021). "Beta coefficient (slope) in the linear relations between CX3CR1 expression and birth weight in the absence of preeclampsia was 1.04 (p = 0.007), but in case of preeclampsia, the decrease of the coefficient beta was − 0.35 (p = 0.015)." (PMID 33496844, 2021). "Beta coefficient (slope) in the linear relations between CX3CR1 expression and vascularization index in the absence of preeclampsia was 0.00079 (p = 0.017), but in case of preeclampsia, the decrease of the coefficient beta was − 0.00029 (p = 0.038)." (PMID 33496844, 2021). "In preeclampsia, the peripheral subpopulation of “non-classical” CD16+ monocytes, which express CX3CR1, is increased in comparison to uncomplicated pregnancies, and they show up-regulation of some immunomodulating factors like clusterin, lipocalin-2 and leptin receptors." (PMID 33496844, 2021).
psoriasis (5 papers, 2010 to 2022). An autoimmune condition characterized by red, well-delineated plaques with silvery scales that are usually on the extensor surfaces and scalp. "CX3CR1 deficiency attenuated imiquimod-induced psoriasis-like skin inflammation with decreased M1 macrophages." (PMID 35837394, 2022). "Two single nucleotide polymorphisms in the CX3CR1 gene were associated with psoriasis and CX3CR1 messenger RNA (mRNA) expression was upregulated in the lesional skin of psoriasis patients, suggesting that CX3CR1 can also be involved in the development of psoriasis." (PMID 33036460, 2020). "Interestingly, 2 polymorphisms in the CX3CR1 gene were found to be associated with psoriasis." (PMID 23468834, 2013). "Furthermore, the importance of the interaction between CX3CL1 and CX3CR1 has been postulated in psoriasis." (PMID 35837394, 2022). "Furthermore, it was recently reported that attenuation of imiquimod-induced psoriasis-like skin inflammation was shown in CX3CR1−/− mice through decrease in M1 macrophages." (PMID 33036460, 2020). "In addition, TNF-α and IL-6 expression were downregulated in unstimulated peritoneal macrophages from CX3CR1−/− mice, consistent with our previous report on imiquimod-induced psoriasis-like skin inflammation model in CX3CR1−/− mice." (PMID 33036460, 2020). "We previously reported that imiquimod-induced psoriasis-like skin inflammation was attenuated in CX3CR1−/− mice through decrease in M1 macrophages but not total macrophages." (PMID 33036460, 2020).
systemic sclerosis (5 papers, 2005 to 2025). A chronic disorder, possibly autoimmune, marked by excessive production of collagen which results in hardening and thickening of body tissues. "This review investigates the role of fractalkine (FKN) and its receptor, CX3CR1, in systemic sclerosis (SSc) pathogenesis." (PMID 39392260, 2024). "In summary, this review aims to highlight the function of CX3CR1 and CX3CL1 (FKN) in systemic sclerosis." (PMID 39392260, 2024).
unstable angina (5 papers, 2019 to 2025). "Levels then returned to those of patients with stable angina by 24 h and the reverse was seen in gene expression of CX3CR1 in patients with acute MI." (PMID 37510939, 2023). "Additionally, Ikejima also demonstrated an increase in levels of monocytes, T lymphocytes, and NK cells, all of which express CX3CR1, and were seen to be elevated in the unstable angina cohort compared to other patient groups." (PMID 37510939, 2023). "Patients with unstable angina and proven unstable plaque disease were found to have significantly higher levels of FKN and mononuclear cells expressing CX3CR1, as compared to stable angina patients or healthy controls." (PMID 37510939, 2023). "CX3CR1, (CCL5/RANTES) and CC chemokine ligand-18 (CCL18/ PARC) are closely related to refractory unstable angina and can be used as a specific marker, while CX3CL1 is used as a marker of response to statin therapy." (PMID 31934638, 2019). "A research detected that patients with stable angina pectoris displayed significantly elevated CD14 + CD16 + CX3CR1 + monocyte counts compared with patients without vulnerable plaques." (PMID 39820843, 2025). "Moreover, patients with unstable angina and unstable plaque have shown higher CX3CL1 levels and increased expression of CX3CR1." (PMID 41153665, 2025).
aortic aneurysm (4 papers, 2024 to 2025). A ruptured aneurysm located in the wall of the proximal portion of the descending aorta proceeding from the arch of the aorta. "Of note, CX3CR1+ macrophages were mainly accumulated in aortic roots and aneurysmal aortas in contrast to nonaneurysmal segments, suggesting a relatively specific association of CX3CR1+ macrophages with the pathogenesis of aortic aneurysm in MFS mice." (PMID 39817456, 2025). "Gene expression of CX3CL1 and CX3CR1 levels are elevated in lesions of aortic aneurysm and aortic dissection, and CX3CL1/CX3CR1 may be involved in these diseases as well, requiring further investigation." (PMID 40508161, 2025).
autism spectrum disorder (4 papers, 2020 to 2022). A spectrum of developmental disorders that includes autism, and Asperger syndrome. "Nevertheless, elevated levels of CX3CR1 and BDNF in microglia were also associated with autism spectrum disorders." (PMID 32765258, 2020).
colorectal tumors (4 papers, 2018 to 2021). "Furthermore, non-classical monocytes require CX3CR1 to infiltrate tumors since Ly6Clo monocytes infiltration in murine orthotopic colorectal tumors is abolished in CX3CR1 KO mice." (PMID 33783686, 2021).
cyst (4 papers, 2022 to 2024). A sac-like closed membranous structure that may be empty or contain fluid or amorphous material. "In the peritoneum, we saw a ~3-fold increase in parasite burden in the Cx3cr1+Casp1 KO mice compared to control mice, which was associated with a greater cyst burden in the brains of these mice at 6 weeks post-infection (6wpi)." (PMID 39446964, 2024). "Collectively, these data suggest that CX3CR1+ macrophages, and a CD206+ subset of these macrophages, are closely associated with cyst formation in the adult-induced Pkd2 mutants." (PMID 36457161, 2023). "Further, we found that Cx3cr1 regulated cortex specific accumulation of Ccr2+ KRM as loss of Cx3cr1 reduced the number of cortical Ccr2+ KRM and delayed cyst progression in a cortex-specific model of cystic kidney disease." (PMID 37256130, 2023). "Reducing renal macrophages using Cx3cr1-deficient mice attenuated cyst severity in adult-induced Pkd2 mutants in the absence of injury." (PMID 36457161, 2023). "Using Cx3cr1 null mice, we reduced macrophage number, including CD206+ macrophages, and showed that this significantly reduced cyst severity in adult-induced Pkd2 mutant kidneys." (PMID 36457161, 2023). "More importantly, analysis of renal histology, cystic index, 2KW/BW and blood urea nitrogen (BUN) indicated that the cyst progression was attenuated, and renal function was improved, in Pkd2 mutant kidneys in the absence of Cx3cr1." (PMID 36457161, 2023). "Thus, our data indicate that Cx3cr1 controls niche specific Ccr2+ KRM accumulation and, in turn, regulates cyst progression in a model that mainly impacts the kidney cortex." (PMID 37256130, 2023). "With this model, we observed that mutation of Cx3cr1 resulted in significant reduction in the number of CD206+ R2 and led to markedly attenuated cyst severity in Pkd2 mutant kidney in the absence of Cx3cr1." (PMID 36457161, 2023). "Importantly, here we show a similar impact on cyst growth related to the reduction of CX3CR1+ macrophages in the adult-induced models in the absence of any exogenous injury." (PMID 36457161, 2023).
gastric cancer (4 papers, 2020 to 2024). A primary or metastatic malignant neoplasm involving the stomach. "The results of the present study suggest that CX3CR1+ cells appearing in the abdominal cavity after gastric cancer surgery are associated with an acute inflammatory response and that these cells may originate from immunosuppressive macrophages and MDSCs." (PMID 38433196, 2024). "We characterized the intraperitoneal immune environment by investigating CX3CR1+ cells in intraperitoneal lavage fluid during gastric cancer surgery." (PMID 38433196, 2024). "We therefore investigated the characteristics and prognostic impact of CX3CR1+ cells in ILF from patients with gastric cancer." (PMID 38433196, 2024). "In various types of cancer, including gastric cancer, reports suggest that CX3CR1 is a poor prognostic factor that promotes metastasis." (PMID 38433196, 2024). "In addition, analysis of intra-abdominal CX3CR1+ cells could be useful for characterizing the immune environment after gastric cancer surgery." (PMID 38433196, 2024).
Hepatitis (4 papers, 2012 to 2023). Inflammation of the liver. "In this study, we have investigated the role of the fractalkine receptor CX3CR1 in modulating monocyte-derived dendritic cell (moDC) differentiation during liver inflammation." (PMID 31540356, 2019).
influenza (4 papers, 2020 to 2024). An acute viral infection of the respiratory tract, occurring in isolated cases, in epidemics, or in pandemics; it is caused by serologically different strains of viruses (influenzaviruses) designated A, B, and C, has a 3-day incubation period, and usually lasts for 3 to 10 days. "In order to identify other potential pathways by which IFNλ delays bacterial clearance during super-infection, we performed bulk RNA sequencing on myeloid cells from influenza-infected CX3CR1-Cre-IFNLR1fl/fl mice." (PMID 39178311, 2024). "To validate our findings from the spatial transcriptomics data, we immunostained aged influenza-infected mouse lungs and identified a similar enrichment of CX3CR1+ monocyte-derived macrophages within Krt8hi areas of dysplastic repair." (PMID 38077031, 2023). "For example, virus-specific cytotoxic T lymphocytes (CTLs) are quickly recruited to influenza-infected lungs by a Th1 response, specifically due to the production of IFNγ Two of these Th1-type effector T-cell chemokine receptors are CXCR3 and CX3CR1." (PMID 34394127, 2021). "Bone marrow cells from naïve mice and lung cells from influenza-infected mice were analyzed by flow cytometry to test whether CCR1 and CX3CR1 could be detected at the protein level." (PMID 32174921, 2020). "Nevertheless, surface expression of CCR1 or CX3CR1 could not be detected on the MCp from influenza-infected lungs." (PMID 32174921, 2020). "However, surface expression of CX3CR1 could not be detected in MCp from naïve mouse bone marrow or influenza-infected lungs, suggesting that the CX3CR1 mRNA is not translated or that post-translational modifications may target the protein for degradation, thus preventing surface expression." (PMID 32174921, 2020).
liver disease (4 papers, 2019 to 2026). "This review provides a systematic and critical examination of the multifaceted roles of the CX3CL1/CX3CR1 axis in liver diseases." (PMID 41716421, 2026). "Therefore, the roles played in tumors by virus-related chemokines may be multiple, and the specific role of CX3CR1 in the formation of chronic hepatitis and liver disease still needs to be further elaborated." (PMID 40733585, 2025). "It cannot, however, be excluded that CX3CR1 may play a role in human intrahepatic inflammatory responses, as human peripheral blood monocytes express high levels of CX3CR1 also in patients with liver disease." (PMID 31798592, 2019). "However, in liver disease, also endothelial-related expression of CX3CL1 may attract CD16+ monocytes CX3CR1-dependently into areas with active inflammation to dampen inflammation and promote resolution of injury." (PMID 31798592, 2019).
malaria (4 papers, 2009 to 2025). Malaria is a serious and sometimes fatal disease caused by a parasite that commonly infects a certain type of mosquito which feeds on humans. "Elevated numbers of CD14hi monocytes which co-express the chemokine receptors CCR2 and CX3CR1 have been associated with lower parasitemia and increased ADCI activity in P. falciparum-infected individuals with uncomplicated malaria." (PMID 26149666, 2015). "The mean level of CCR2 and CX3CR1 expression on the total blood MO was three times higher in patients with acute uncomplicated malaria (18.5±1.5%) than in healthy malaria exposed individuals (6.0±4.8%)." (PMID 19851453, 2009). "Group 2 patients, characterized by a percentage of CD14hi CCR2+CX3CR1+ MO similar to that of healthy malaria exposed individuals, had a pro-inflammatory phenotype, a trend for higher levels of plasma cytokines, and a 10 fold higher mean peripheral parasitemia." (PMID 19851453, 2009). "Patients' MO had significantly lower percentages of CD56 and mIFN-γ and higher percentages of CCR2+CX3CR1+ than malaria-exposed individuals, and high expression of the inflammatory marker TREM-1." (PMID 19851453, 2009). "Notably, CD16+ Vδ2 T cells from malaria-exposed individuals phenotypically resemble mature NK cells, including expression of the cytolytic effector molecules perforin, granzyme B and granulysin, as well as CX3CR1 and KIRs, and down-regulation of IL18R." (PMID 33085728, 2020). "Examining malaria-experienced individuals for common markers across all assays, 4-1BB+, CTLA-4+, CX3CR1+, NKG2C+, TIM-3+, and Siglec-7– NK cells were enriched for IL-10 production." (PMID 40337867, 2025). "In healthy malaria exposed individuals, the percentage of CD14hi CCR2+CX3CR1+ MO was low (mean value: 5.23±4.49%, 95% CI: 1.84–8.62)." (PMID 19851453, 2009).
myocarditis (4 papers, 2017 to 2025). Myocarditis is a condition that is characterized by inflammation of the heart muscle (myocardium). "Our observations allow us to conclude that CX3CR1 emerges to be cardioprotective in the pathogenesis of CVB3-induced myocarditis since CX3CR1-/- mice were more susceptible to CVB3 infection as WT animals." (PMID 28800592, 2017). "Similarly, deficiency of other chemokine receptors, CCR5 or CX3CR1, leads to aggravated pathogen-induced myocarditis described by increased mortality or impaired cardiac function." (PMID 39195892, 2024). "Conversely, the disruption of the CX3C chemokine receptor 1 (CX3CR1)-CX3C chemokine ligand 1 (CX3CL1) axis has been shown to exacerbate CVB3-induced myocarditis." (PMID 40284927, 2025). "This follows from the findings that CX3CR1-/- CVB3 mice exhibited an exacerbated CVB3-induced myocarditis as shown by a higher LV MCP-1 and CCR2 expression, more cardiac infiltrates, and higher cytokine levels versus CVB3-infected WT mice." (PMID 28800592, 2017). "We therefore investigated the influence of CX3CR1 ablation in the model of acute myocarditis, which was induced by inoculation with 5x105 plaque forming units of CVB3 (Nancy strain) in either CX3CR1-/- or C57BL6/j (WT) mice." (PMID 28800592, 2017). "In the present study, we could demonstrate that CX3CR1 plays a critical role in the pathogenesis of CVB3-induced myocarditis." (PMID 28800592, 2017). "Furthermore, CX3CR1 seems to control the CCR2/MCP-1-dependent pathway, since CX3CR1 ablation resulted in an exacerbation of CVB3-induced myocarditis." (PMID 28800592, 2017). "Finally, we conclude that the modulation of the CX3CL1/CX3CR1 axis could be a new important target in the treatment of CVB3-induced myocarditis." (PMID 28800592, 2017). "Nevertheless, the role of the chemokine receptor CX3CR1 has not been unraveled yet in experimental CVB3-induced myocarditis." (PMID 28800592, 2017). "Since the CX3CR1/CX3CL1 system is upregulated in inflammatory cardiomyopathy and has chemotactic properties, we examined the impact of CX3CR1-/- on cardiac chemokine receptor and chemokine expression in CVB3-induced myocarditis." (PMID 28800592, 2017). "Given the impact of CX3CR1-/- on cardiac inflammation, fibrosis, N2B titin, and apoptosis in CVB3-infected myocarditis mice, we next evaluated whether these effects were translated in changes in left ventricular function." (PMID 28800592, 2017). "Conform to the systemic increased CX3CR1 expression in peripheral blood mononuclear cells of CVB3-positive inflammatory cardiomyopathy patients, an upregulation in CX3CR1 mRNA expression was found in the spleen of CVB3-infected myocarditis compared to control mice." (PMID 28800592, 2017).